MGMT (O-6-methylguanine-DNA methyltransferase)
Diseases named in the same sentence as MGMT in open-access papers (continued):
Sharing a sentence is not in itself a finding about the gene and the disease.
glioblastoma (continued). "Repressed O6-methylguanine-DNA methyltransferase (MGMT) by promoter methylation is a prognostic biomarker in glioblastoma (GBM)." (PMID 26101774, 2015). "In addition, the novel regulatory miR-603, which directly interacts with the 3′-UTR region of MGMT gene, produced a 6-fold decrease of both MGMT mRNA and protein upon transfection in glioblastoma cell line in vitro and sensitized glioblastoma cells to temozolomide." (PMID 26035292, 2015). "Since the introduction of temozolomide (TMZ) chemotherapy in the standard care protocol for glioblastoma (GBM) patients, the analysis of O6-methylguanine DNA methyltransferase (MGMT) status has become a key biological marker." (PMID 24420923, 2014). "In this work, we have used Western blotting to examine the effect of inhibiting mTORC1/2 signalling on steady state MGMT protein levels in T98G GBM cells, a cell line which exhibits relatively high MGMT expression compared to other glioblastoma cell lines." (PMID 24909675, 2014). "Also the predictive value of the MGMT promoter methylation status seen in elderly glioblastoma patients in the NOA-08 and the Nordic glioma trials could be reproduced using pyrosequencing." (PMID 24359605, 2014). "As mutations in the mTOR signalling pathway in GBM frequently result in hyperactive PI3-K/mTOR signalling, promoting cell survival and protein synthesis, we investigated whether mTOR kinase activity has a role in regulating levels of MGMT protein expression in human glioblastoma cells." (PMID 24909675, 2014). "Given the heterogeneity of clinical glioblastoma specimens, we further correlated these data with tumour cell morphological subtypes, specific patterns of vascular proliferation and known genetic prognostic markers such as IDH1 mutation and MGMT promoter methylation." (PMID 23990986, 2013). "Because MGMT methylation was suggested as a pivotal prognostic factor for OS of glioma patients who were treated with temozolomide, we established Cox models for all glioblastoma patients, patients treated with temozolomide as well as patients without temozolomide application, respectively." (PMID 24380367, 2013). "Contrary to this, we could not find any relation of the C-56 T MGMT polymorphism to overall survival of our patient cohort, again arguing against a fundamental role of MGMT in the prognosis of glioblastoma patients as seen by our MGMT promoter methylation analysis." (PMID 24380367, 2013). "Hence the present study could provide a new step for establishing the involvement of MGMT status in glioblastoma, taking into account the importance of the differentiation status of cells in response to TMZ and alkylating agents." (PMID 22837675, 2012). "A link was observed in GBM between MGMT promoter methylation and a hypermutator phenotype as a consequence of a mismatch repair deficiency in treated glioblastomas, a finding with potentially significant clinical implications." (PMID 22778947, 2012). "Patients from the TCGA-GBM dataset (n = 239) with a MGMT methylated glioblastoma had a more favorable outcome (p = 0.047, log-rank test)." (PMID 22810491, 2012). "Expression of MGMT and DNMTs mRNA were analysed by real-time qPCR.Prognostic factors were obtained from proportional hazards models.Correlation between MGMT mRNA expression and MGMTmethylation status was validated using data from the Cancer Genome Atlas(TCGA) database (N = 229 glioblastomas)." (PMID 21365007, 2011). "Moreover, RECQ1 protein overexpression does not seem to have a prognostic value associated with MGMT methylation status in primary glioblastoma multiforme." (PMID 21752281, 2011). "While several clinical trials have already confirmed the effect of MGMT hypermethylation on chemotherapy resistance in gliomas and glioblastomas, the MethMarker-optimized biomarker may facilitate the clinical confirmation of MGMT's predictive role in other cancers." (PMID 19804638, 2009).
glioblastoma (continued). "The reproducibility of MGMT as a predictive biomarker will be prospectively validated as part of the ongoing EORTC/NCI/RTOG (EORTC protocol 26052–22053) phase III study comparing conventional adjuvant temozolomide with dose-intense temozolomide in patients with newly diagnosed glioblastoma." (PMID 22275966, 2008). "All tumors were histologically confirmed as glioblastoma (IDH-wildtype) and in 22 of 30 patients (73%) the MGMT promoter was methylated." (PMID 41575548, 2026). "A woman, in her mid-50s, presented with headache, confusion, and unstable gait due to a large right parietal mass subsequently diagnosed histologically as glioblastoma, IDH-wildtype, CNS WHO Grade 4 with an unmethylated MGMT promoter." (PMID 42294267, 2026). "In glioblastoma multiforme (GBM), MGMT promoter methylation is a well-established biomarker for predicting the effectiveness of the alkylating agent TMZ." (PMID 40895460, 2025). "In recent years, several molecular targets, such as MGMT, PARP, and APE-1, have been identified as potential strategies to overcome temozolomide resistance in glioblastoma." (PMID 39903772, 2025). "Temozolomide (TMZ) is the current standard chemotherapy for glioblastoma (GBM), yet its therapeutic efficacy is severely hampered by poor chemical stability, and frequent development of resistance, particularly through MGMT upregulation." (PMID 40429865, 2025). "We observed some associations without stratifying samples by their MGMT promoter methylation status, while others were found in subgroups (either methylated or unmethylated MGMT promoter samples), underscoring the importance of MGMT promoter methylation in glioblastoma." (PMID 40244270, 2025). "Assessing MGMT status involves invasive tissue sampling, which carries surgical risks and can be confounded by intratumoral heterogeneity, particularly in glioblastoma (GBM)." (PMID 41584616, 2025). "Final pathology revealed glioblastoma (IDH-1) wildtype, O6-methylguanine-DNA-methyltransferase (MGMT) unmethylated CNS WHO Grade IV tumor." (PMID 41356860, 2025). "Recent studies suggest that MGMT expression not only affects tumor sensitivity to therapy but also plays a nuanced role in shaping the TIME, particularly in glioblastoma and other aggressive malignancies." (PMID 40895460, 2025). "DCVax-L has demonstrated significant clinical benefits in glioblastoma treatment, with phase III trial data showing mOS of 19.3 months for ndGBM patients overall, 30.2 months for MGMT-methylated ndGBM patients, and 13.2 months for rGBM patients." (PMID 40386781, 2025). "The histopathology report stated that the obtained tissue was a glioblastoma, isocitrate dehydrogenase (IDH)-wildtype, WHO grade IV, O6-methylguanine-DNA methyltransferase (MGMT) un-methylated with a telomerase reverse transcriptase (TERT) mutation." (PMID 39860615, 2025). "Nonetheless, glioblastoma (GBM) cells with low levels of MGMT still show resistance to TMZ, suggesting that MGMT‐independent mechanisms are also involved in the initial or acquired resistance to TMZ." (PMID 39873425, 2025). "In this context, we report on a 60-year-old woman with a right frontal glioblastoma, IDH wildtype, MGMT methylated." (PMID 39843784, 2025). "ATRX, OLIG2, MGMT, and IDH2 were selected due to their critical roles in glioblastoma biology and prognosis." (PMID 40282990, 2025). "These molecular findings allowed the classification of the tumors as “Glioblastoma, IDH-wildtype, WHO grade 4,” of which 40% (4 out of 10) had MGMT promoter hypermethylation." (PMID 41567539, 2025).
glioblastoma (continued). "Glioblastoma (GBM) is the most malignant subtype of glioma and the methylation status of the Methylguanine-DNA Methyltransferase (MGMT) was proven to be a crucial factor to select the most appropriate therapy, which is currently assessed through brain biopsy." (PMID 41228211, 2025). "Methylation of the MGMT promotor was detected in 38.1% of all IDH-wt astrocytomas, and 49.0% of all IDH-wt glioblastomas (p = 0.0579)." (PMID 41466163, 2025). "In temozolomide (TMZ)-resistant glioblastoma multiforme (GBM), miR-101 downregulation led to GSK3β upregulation, promoting O6-methylguanine-DNA methyltransferase (MGMT) expression and resistance, while miR-101 overexpression sensitized cells to TMZ." (PMID 40074445, 2025). "O6-methylguanine-DNA methyltransferase (MGMT) promoter methylation, present in approximately 45% of IDH-wildtype glioblastomas and 50–70% of IDH-mutant gliomas, emerged as the key predictive biomarker for treatment response." (PMID 41511341, 2025). "PARP physically binds with poly (ADP) ribosylates MGMT in mice when combined with TMZ, providing a rationale for combining PARP inhibitors with TMZ for glioblastoma." (PMID 41149461, 2025). "To expand the screening for agents capable of reducing TMZ resistance in glioblastoma, we examined the effects of eight compounds (with IC50 values below 30 μM in LN‐229 cells) on MGMT expression in MGMT‐overexpressing HEK293FT cells." (PMID 40990506, 2025). "Key molecular players, such as ATRX, OLIG2, MGMT, and IDH2 proteins, contribute to critical oncogenic processes like chromatin remodelling, glioblastoma cell fate and de-differentiation, DNA repair and metabolic reprogramming." (PMID 40282990, 2025). "For GSM, our data shows that MGMT promoter methylation is also prognostically relevant and TMZ‐based chemotherapy improves survival, as it does for glioblastoma." (PMID 39545524, 2024). "TRIM24, through PI3K/AKT/NF-κB signaling, controls the expression of the DNA repair enzyme O6-methylguanine-DNA methyltransferase (MGMT), contributing to increased resistance to temozolomide, the standard chemotherapeutic agent for glioblastoma." (PMID 39160596, 2024). "On the other hand, IDH-wildtype glioblastoma cases that expressed PRMT5 and had unmethylated MGMT-promoter, who received TMZ treatment, have experienced early tumor recurrence." (PMID 38827324, 2024). "In the whole series, 36 (90%) tumors were TERT-mutant (including 32 glioblastomas IDH wild type and 4 oligodendrogliomas) and the MGMT promotor was methylated in 33 (75%) cases." (PMID 39456559, 2024). "This adduct can be removed by the DNA repair protein O6-methylguanine-DNA-methyltransferase (MGMT), which is heterogeneously expressed in glioblastoma and whose gene transcription is epigenetically silenced by the methylation of its promoter." (PMID 39408901, 2024). "These metrics were used to assess the performance of the models in both the glioblastoma ROI patches prediction module and the MGMT promoter status prediction module." (PMID 38385046, 2024). "When MMR is expressed, human glioblastoma cells are TMZ-sensitive, and when MGMT, BER, and APNG proteins are expressed, then the cells develop resistance to TMZ." (PMID 39457529, 2024). "MGMT promoter methylation status predicts responsiveness to TMZ; patients harboring unmethylated MGMT (~60% of glioblastoma) have a poorer prognosis with limited treatment benefits from TMZ." (PMID 38224404, 2024). "A phase II trial for glioblastoma (GBM) patients with MGMT unmethylation reported that the mTOR inhibitor temsirolimus could prolong overall survival in patients with mTORSer2448 phosphorylation." (PMID 37545464, 2024). "Moreover, in 91 patients with unknown MGMT promoter status, the hazard ratio for death was significantly increased, suggesting that the MGMT promoter status plays an important role for survival not only in glioblastoma but also in GSM." (PMID 39545524, 2024).
glioblastoma (continued). "Postoperative pathology and genetic examination confirmed the diagnosis of glioblastoma [World Health Organization (WHO) stage IV], with an IDH wild-type genotype and a positive methylation status of the MGMT promoter." (PMID 39295944, 2024). "However, survival curves between MGMT-methylated and MGMT-unmethylated glioblastomas diverge starting from nine months and, suggesting that other factors may contribute to predict survival in the MGMT-methylated glioblastomas." (PMID 38454929, 2024). "Recent studies suggested that NDRG1 positively regulates and stabilizes DNA repair enzymes MGMT, APEX1, and PKNP, thereby driving temozolomide (TMZ) resistance in human glioblastoma and acute lymphoblastic leukemia (AML)." (PMID 38970106, 2024). "The findings of the PPI network analysis suggested that the key targets of naringin in the chemosensitization of glioblastoma would be PARP-1, MGMT, and caspases." (PMID 39148542, 2024). "In recent years, clinical studies on glioblastoma and mCRC patients have used methylation-specific PCR (MSP) to assess MGMT gene methylation." (PMID 39594133, 2024). "The methylated MGMT promoter has garnered substantial support as a predictive marker for the effectiveness of temozolomide (TMZ), an alkylating agent used in treating glioblastoma and low-grade gliomas." (PMID 38254819, 2024). "Previous studies have identified the MGMT promoter has been identified as a biomarker of TMZ in both IDH‐wildtype and IDH‐mutant glioblastoma." (PMID 38970209, 2024). "Anatomical characteristics, such as tumor location and laterality, have been compared with specific molecular alterations in glioblastomas, including VEGF and MGMT." (PMID 39684754, 2024). "The methylation of the O6-Methylguanine-DNA Methyltransferase (MGMT) promoter is a valid biomarker for predicting response to therapy with alkylating agents and, independently, prognosis in IDH-wildtype(IDH-w) glioblastoma." (PMID 39367282, 2024). "First-line treatment for glioblastoma is radiotherapy combined with TMZ or lomustine, possibly combined with TTF, based on patient fitness and MGMT promoter methylation status." (PMID 38571509, 2024). "Patients with de novo glioblastomas with a methylated MGMT promoter benefited from temozolomide, whereas those with TERT unmethylated mutant-MGMT had a poorer prognosis." (PMID 39586842, 2024). "We included patients with diagnosis of isocitrate dehydrogenase wild-type glioblastoma [World Health Organization (WHO) 2021 classification], available pre-surgical MRI, known MGMT promoter methylation status." (PMID 39713243, 2024). "Key factors influencing glioblastoma prognosis include patient age at surgery, KPS at admission, the extent of tumor resection in terms of STR and GTR, MGMT promoter methylation status und IDH-status." (PMID 39340649, 2024). "The majority of IDH-mutant astrocytomas possess methylated MGMT promoters, and compared to IDH-wildtype glioblastomas, IDH-mutant tumours show significantly higher MGMT promoter methylation." (PMID 37239289, 2023). "Consequently, the methylation status of the MGMT promoter has emerged as a useful biomarker for predicting the treatment response of glioblastoma (GBM) patients to methylating chemotherapeutic agents like temozolomide." (PMID 37229486, 2023). "In glioblastoma, DCA has been reported to enhance the activity of the DNA repair enzyme O6-methylguanine-DNA methyltransferase (MGMT), thereby increasing the sensitivity of glioblastoma cells to temozolomide, a standard chemotherapeutic agent." (PMID 37359381, 2023).
glioblastoma (continued). "Here, based on the DNA methylation status of the O6-methylguanine-DNA methyltransferase (MGMT) gene promoter region, the clinical response of glioblastomas to temozolomid chemotherapy clearly differs and, therefore, affects the choice of chemotherapy." (PMID 36765639, 2023). "Glioblastoma multiforme (GBM) is probably the only tumor in which a unique epigenetic alteration, namely methylation of the MGMT gene, possesses direct clinical relevance." (PMID 37821547, 2023). "MGMT and phosphorylated-STAT3 levels increase in recurrent tumors compared to primary glioblastoma patients." (PMID 38264122, 2023). "For glioblastoma patients receiving the treatment of temozolomide (TMZ), the O6-methylguanine DNA methyltransferase (MGMT) promoter methylation status is a prognostic predictor." (PMID 37170390, 2023). "Among glioblastomas- IDH wildtype, methylation of MGMT promoter was observed in 34.6% (28/81) cases." (PMID 39760063, 2023). "Molecular profiles similarly indicated a poor-risk biological cohort including predominance of IDH-1 wild type (85.7%), MGMT unmethylated (57.1%) tumors with EGFR, PTEN, and CDKN2A profiles in keeping with molecular glioblastoma." (PMID 36402744, 2023). "She underwent biopsy of a left hippocampal lesion that was consistent with WHO grade 4 diffuse astrocytic glioma with molecular features of glioblastoma based on polysomy chromosome 7 and monosomy chromosome 10, IDH-wildtype, MGMT promoter unmethylated." (PMID 37215950, 2023). "For example, the CATNON trial found no benefit of combined TMZ and radiotherapy versus radiotherapy alone in glioblastoma, IDH wild type patients, and while MGMT methylation status was predictive of patient survival it did not predict response to TMZ." (PMID 36632958, 2023). "In TMZ-resistant glioblastoma with high expression of MGMT, the repression of the HH signalling pathway by PF403 also reduced MGMT expression." (PMID 36675073, 2023). "Among patients with IDH-wild-type glioblastoma and a high [18F]GE180 SUVmax, slightly more tumors (11/21) were MGMT-methylated than in the subgroup of patients with a sub-median SUVmax (8/20)." (PMID 36329288, 2023). "The primary human glioblastoma lines NULU and ZAR, selected based on the methylation profile (unmethylated MGMT) and therefore resistant to treatment with alkylating drugs, were exposed to a combination of AE 20 μM and TMZ 10 μM for 24, 48, and 72 h." (PMID 37630276, 2023). "In our study, there was a tendency for MGMT overexpression in iPSCs induced with a U87MG monolayer CM and GLI2 was found to be over expressed, which confirmed these as iPSC-derived glioblastoma-like cells." (PMID 37509281, 2023). "For example, two distinct communities, Blocks 1 and 6, with the same diagnosis—glioblastoma, IDH-wildtype—yielded rather different hazard ratios: 2.76 versus 2.27, the former more likely to exhibit MGMT methylation and high EGFR amplification than the latter." (PMID 37665980, 2023). "Integrated molecular histopathology revealed the lesion to be a Glioblastoma WHO grade IV, IDH wild type, MGMT methylated." (PMID 36625909, 2023). "This patient was diagnosed with a glioblastoma, IDH wild type, MGMT unmethylated, in January 2016 and completed primary chemoradiation in March 2016." (PMID 37104141, 2023). "In glioblastoma, the combination of IDH and MGMT status is more predictive of survival than IDH or MGMT alone." (PMID 35806478, 2022). "The median value of MGMT promoter methylation was 14 (IQR: 6.5–31.5) and all glioblastomas were wildtype for IDH." (PMID 35326565, 2022). "Advanced MRI, including arterial spin labeling imaging (ASL), DWI, and dynamic susceptibility contrast perfusion imaging (DSC), is used to assess MGMT and TERT status in patients with glioblastomas." (PMID 36471242, 2022). "Methylation of the MGMT promoter results in gene silencing and correlates with better outcome in TMZ-treated glioblastoma patients." (PMID 36585418, 2022).